OR2A4 (olfactory receptor family 2 subfamily A member 4)
Description:
Odorant receptor.
Synonyms: OR2A10
Tractability: Antibody: UniProt places it where antibodies can reach, with medium confidence; UniProt predicts a signal peptide or a membrane-spanning region; its Gene Ontology location is reachable by antibodies, with medium confidence.
Gene: Protein-coding gene on chromosome 6 (131,699,644 to 131,701,401, reverse strand). Ensembl gene ENSG00000180658.
Subcellular location: Cell membrane
Pathways (Reactome):
Sensory Perception: Expression and translocation of olfactory receptors
Gene Ontology:
Molecular function: odorant binding; olfactory receptor activity; G protein-coupled receptor activity
Biological process: positive regulation of cytokinesis; regulation of actin cytoskeleton organization; detection of chemical stimulus involved in sensory perception of smell; G protein-coupled receptor signaling pathway
Cellular component: cleavage furrow; Flemming body; mitotic spindle midzone; mitotic spindle pole; recycling endosome; membrane; plasma membrane
Genetic constraint (gnomAD): Missense variants: 63 observed, 95.53 expected, observed/expected ratio (o/e) 0.66, 90% interval 0.54 to 0.81. Synonymous variants: 28 observed, 36.48 expected, observed/expected ratio (o/e) 0.77, 90% interval 0.57 to 1.05.
Homologues: Orthologues: dog OR2A7 (84% identical), mouse Or2a7 (81% identical), rat Or2a7 (80% identical). Paralogues in human: OR2A7 (99% identical), OR2A25 (79% identical), OR2A1 (70% identical), OR2A42 (70% identical), OR2A5 (65% identical), OR2A12 (60% identical), OR2A14 (60% identical), OR2A2 (59% identical), OR7A10 (43% identical), OR1C1 (42% identical), OR1F1 (42% identical), OR7C1 (42% identical), and 116 more.
Diseases named in the same sentence as OR2A4 in open-access papers:
OR2A4 is named in the same sentence as 2 diseases in open-access papers, as found by Europe PMC text mining. Sharing a sentence is not in itself a finding about the gene and the disease. The quoted sentences say what the papers report.
cervical cancer (1 paper, 2017). A primary or metastatic malignant neoplasm involving the cervix. "However, the function was only hypothesized except for OR2A4 in cells derived from cervical cancer, where participation in the cytokinesis was shown experimentally." (PMID 29249973, 2017).
OR2A4 also shares sentences with these, for which no sentence is quoted: diabetes (1 paper).